VCAM1 (vascular cell adhesion molecule 1)
Diseases named in the same sentence as VCAM1 in open-access papers (continued):
Sharing a sentence is not in itself a finding about the gene and the disease.
lupus nephritis (23 papers, 2010 to 2025). Glomerulonephritis in the context of systemic lupus erythematosus. "Urinary VCAM-1 emerges as a reliable indicator of the activity:chronicity ratios that mark the underlying renal pathology in lupus nephritis." (PMID 22788914, 2012). "Urinary levels of IL-18 and VCAM-1 were reported to be increased and associated with pathological events in lupus nephritis, so MAIT cells may also migrate into inflamed tissues in SLE." (PMID 28288675, 2017). "They found varying degrees of increased VCAM1 expression in renal tubular epithelial cells of patients with crescentic nephritis, vasculitis, lupus nephritis, and IgA nephropathy." (PMID 40369957, 2025). "In these animals, B cell recruitment occurs during the development of lupus nephritis and is associated with abnormal expression of CXCL13 and adhesion molecules, such as PNAd, ICAM and VCAM-1 in the blood vessels of PVS." (PMID 39483979, 2024). "In an animal study utilizing the MRL/lpr murine model of lupus nephritis, increased expression of VCAM1 was observed in the endothelium, cortical tubules, and glomeruli of the kidneys." (PMID 39319258, 2024). "Comparison of syndecan-1, hyaluronan, thrombomodulin and VCAM-1 as putative biomarkers for lupus nephritis compared to conventional serological and clinical markers of disease." (PMID 37854589, 2023). "Among active lupus nephritis patients, urine VCAM-1 (r 0.57, P<0.0001), ALCAM (r 0.53, P<0.0001) and PF4 (r 0.50, P<0.0001) exhibited the best correlations with renal SLEDAI." (PMID 35720325, 2022). "According to an animal study, MRL/lpl (a murine model of lupus nephritis) kidneys display increased VCAM1 expression in the endothelium, cortical tubules and glomeruli." (PMID 34506229, 2021). "The increase of VCAM-1 was verified not only in the endothelium, but also in cortical tubules and glomeruli of murine lupus nephritis models." (PMID 33292825, 2020). "Vascular cell adhesion molecule-1 (VCAM-1) is involved in the progression of glomerular and tubulointerstitial injury in lupus nephritis (LN) and can be easily assessed in urine." (PMID 33292825, 2020). "In order to demonstrate the applicability of the technique for POC and companion diagnostics, we performed validation studies with ELISA to detect VCAM-1 in a total of 12 lupus nephritis patient urine samples." (PMID 28884017, 2017). "The importance of adhesion molecules in the pathogenesis of lupus nephritis was suggested by the observation that expression of vascular cell-adhesion molecule-1 (VCAM-1) and intercellular adhesion molecule-1 (ICAM-1) are elevated in affected kidneys." (PMID 25400916, 2013). "Vascular cell adhesion molecule 1 (VCAM-1) is an endothelial adhesion and inflammatory molecule that has been reported to play an important role in lupus nephritis." (PMID 23460853, 2013). "CXCL16, MCP-1, and VCAM-1 levels were measured in urine samples from 74 lupus nephritis patients and 13 healthy volunteers." (PMID 22788914, 2012). "In animal models, VCAM-1 expression is considered a major early event in the atherosclerotic process, and increased sVCAM-1 levels have been reported in lupus nephritis." (PMID 22962622, 2012). "sTNFR and circulating VCAM-1 have previously been reported to be increased in SLE in association with flares and higher disease activity, and sTNFR-2 can be a marker of kidney damage in lupus nephritis." (PMID 29482604, 2018). "Furthermore, JKAP-deficient T cells overproduced complement components, soluble ICAM-1, and soluble VCAM-1 in the kidney; these cytokines have been reported to be involved in lupus nephritis." (PMID 27557500, 2016). "VCAM-1 may be a useful biomarker for renal disease activity and supplement current indirect markers of lupus nephritis." (PMID 24647443, 2014). "Normalized fluorescence intensity values for the five biomarkers (ALCAM, OPN, TNFRSF1B, VCAM1, and VSIG4) were compared between healthy controls (HCs) and lupus nephritis (LN) patient groups." (PMID 40047601, 2025).
lupus nephritis (continued). "Indeed, the urinary VCAM-1 level has been shown to be a good marker of renal disease in both anti-GBM disease and spontaneous lupus nephritis." (PMID 23460853, 2013). "Moreover, several studies have shown that levels of soluble VCAM-1(sVCAM-1) and ICAM-1(sICAM-1) are also significantly increased in the serum and urine of patients with lupus nephritis and significantly correlate with disease activity indices." (PMID 25400916, 2013).
pancreatic cancer (23 papers, 2010 to 2025). "As reported in our work, we examined the aberrant expression of VCAM-1, its association with clinicopathological characteristics and patients’ prognosis, and its biological effects on pancreatic cancer in vitro and in vivo." (PMID 29670110, 2018). "TAMs secrete cytokines and chemokines, such as CCL18, which upregulates VCAM-1 in pancreatic cancer via the CCL18/PITPNM3/NF-κB/VCAM-1 pathway, promoting tumor progression." (PMID 40443678, 2025). "In pancreatic cancer, lactate production induced by VCAM-1 from pancreatic cancer cells with enhanced aerobic glycolysis activated macrophages to a TAM-like phenotype." (PMID 40071851, 2025). "Accordingly, highly glycolytic pancreatic cancer cells produce vascular cell adhesion molecule-1 (VCAM-1)." (PMID 39227970, 2024). "On the other hand, TAMs will also secrete chemokines including CCL20 and CCL18, induce the upregulation of matrix metalloproteinase 9 (MMP9) and vascular cell adhesion molecule 1 (VCAM-1) expression in pancreatic cancer cells, and enhance metastasis." (PMID 36726981, 2022). "In turn, VCAM-1 induced pancreatic cancer cells to produce lactic acid and aerobic glycolysis, which promoted the TAM-like phenotype of macrophages to form a positive feedback loop." (PMID 35651786, 2022). "Some types of cancer cells, such as pancreatic cancer cells, secrete VCAM1, which attracts macrophages to the tumor environment." (PMID 34526555, 2021). "Reciprocally, VCAM-1-induced lactate production by pancreatic cancer cells polarizes macrophages towards an alternatively-activated endotype, thus forming a regulatory feedback loop within the tumor microenvironment." (PMID 34201127, 2021). "Macrophage-derived CCL18 also enhances the invasive ability of pancreatic cancer cells by inducing VCAM-1 expression." (PMID 34201127, 2021). "VCAM-1 expression in pancreatic cancer cells also promotes Warburg metabolism, and the lactate released in turn stimulates macrophages to a more immunosuppressive TAM phenotype higher in Cd206, Cd163, and IL-10." (PMID 35008355, 2021). "To see the effect of VCAM-1 on gemcitabine resistance in pancreatic cancer in vitro, we treated K399 cells with VCAM-1 overexpression or knock-down with gemcitabine." (PMID 33273652, 2020). "While we showed VCAM-1 was expressed in the cancer cells in pancreatic cancer tissue by immunohistochemistry, some of the stromal cells were observed expressing VCAM-1." (PMID 33273652, 2020). "In human pancreatic cancer tissues, tumor cells were found expressing VCAM-1 protein in 16 cases out of 20 cases, consistent with previous reports." (PMID 33273652, 2020). "We analyzed plasma samples from a genetically engineered mouse model of pancreatic cancer and found soluble vascular cell adhesion molecule-1 (sVCAM-1) increases in response to gemcitabine treatment." (PMID 33273652, 2020). "We generated a VCAM-1-overexpressing pancreatic cancer cell line using a PDAC cell line established from PKF mice (K399) by lentiviral infection." (PMID 33273652, 2020). "The VCAM-1 in the pancreatic cancer cells induces Warburg effect by increased lactate production resulting in glycolytic phenotype in pancreatic tumors resulting in active TAM-like phenotype." (PMID 30925924, 2019). "A cell adhesion molecule VCAM-1 is reported to be overexpressed in PDAC tissues as well as in cell lines and is associated with clinical outcome of pancreatic cancer." (PMID 30925924, 2019). "Recent report shows the effects of upregulated CCL18/PITPNM3/NF-kB/VCAM-1 signalling cascade in the pancreatic tumor progression." (PMID 30925924, 2019). "In conclusion, we demonstrated that CCL18-positive TAMs were important in malignant progression and induced a glycolytic phenotype in pancreatic cancer, partially owing to paracrine induction of VCAM-1 in PDAC cells." (PMID 29670110, 2018).
pancreatic cancer (continued). "Reciprocally, VCAM-1-induced lactate production from pancreatic cancer cells with enhanced aerobic glycolysis activates macrophages to a TAM-like phenotype, forming a positive feedback loop." (PMID 29670110, 2018). "Here, we show that CCL18 secreted by TAMs facilitates malignant progression and induced a glycolytic phenotype in pancreatic cancer, partially owing to paracrine induction of VCAM-1 in pancreatic cancer cells." (PMID 29670110, 2018). "PAK1&4KO markedly increased ICAM-1 and VCAM-1 expression in pancreatic tumour tissues while decreasing the expression of ICAM-1 and VCAM-1 by cancer cells, indicating that PAK1&4KO upregulated the ICAM-1 and VCAM-1 in tumour stromal cells rather than the tumour cells." (PMID 41228228, 2025). "Of note, preclinical studies showed that inhibition of VCAM1 may be an effective therapeutic option against pancreatic cancer." (PMID 36359790, 2022). "TAMs may upregulate VCAM-1 in pancreatic cancer cells via secretion of CCL18, resulting in increased migration, invasion, and survival." (PMID 35008355, 2021). "We also knocked down VCAM-1 in murine pancreatic cancer cells by shRNA." (PMID 33273652, 2020). "To examine whether sVCAM-1 promotes gemcitabine resistance in pancreatic cancer in vivo, we treated VCAM-1-overexpressing allograft tumors or control tumors with gemcitabine." (PMID 33273652, 2020). "VCAM-1 was expressed and secreted by murine and human pancreatic cancer cells." (PMID 33273652, 2020). "To determine whether pancreatic cancer tissue express VCAM-1 and which type of cells express it, we immunohistochemically stained human and murine pancreatic cancer tissues for VCAM-1." (PMID 33273652, 2020). "However, little is known about the clinical and biological function of VCAM-1 in pancreatic cancer thus far." (PMID 29670110, 2018). "In this study, our work provides the valid evidence for reciprocal signaling interactions between TAMs and pancreatic cancer cells, shedding new light on the utilization of CCL18/PITPNM3/NF-kB/VCAM-1 axis as a potential novel therapeutic target for the treatment of pancreatic cancer." (PMID 29670110, 2018). "In addition to stellate cells, pancreatic cancer cells, hepatocytes and some inflammatory cells were also positive for VCAM1." (PMID 20416094, 2010). "Interestingly, PAK4KO reduced the ICAM-1 expression in pancreatic cancer cells, while the VCAM-1 expression was unaffected compared to the WT, showing that the upregulated ICAM-1 and VCAM-1 in the gemcitabine-treated PAK4KO tumours were expressed in stroma cells rather than cancer cells." (PMID 41294859, 2025). "However, the role of VCAM-1 in pancreatic cancer remains elusive." (PMID 29670110, 2018). "Hence, we identified VCAM-1 as a gene of interest and set out to determine whether VCAM-1 facilitates malignant progression of pancreatic cancer and participates in the cross-talk between tumor cells and TAMs." (PMID 29670110, 2018). "The inhibition of PAK1 or PAK4 suppresses pancreatic cancer by stimulating anti-tumour immunity through the activation of T cells and dendritic cells through ICAM-1 and VCAM-1 upregulations." (PMID 41294859, 2025). "Our study provides the first connection between CCL18/PITPNM3/NF-kB/VCAM-1 axis and PDAC progression and the Warburg effect, raising the possibility of new options for clinical interventions for pancreatic cancer patients." (PMID 29670110, 2018). "Our results demonstrate that the proadhesion molecules E-selectin, ICAM-1, and VCAM-1, the pro-inflammatory IL-1β and MCP-1, and the prometastasis gene MMP-9 are BCL-6-regulated genes in human pancreatic cancer cells." (PMID 23737761, 2013). "PAK4KO enhanced the expression of ICAM-1 and VCAM-1 in tumour tissues by 3 and 4 times, respectively, but not by the pancreatic cancer cells, indicating that PAK4KO specifically stimulated the expression of ICAM-1 and VCAM-1by the non-cancer stromal cells." (PMID 40943273, 2025).
pancreatic cancer (continued). "Subcutaneous allograft tumors with overexpression or knock-down of VCAM-1, as well as VCAM-1-blocking treatment in the spontaneous mouse model of pancreatic cancer, revealed that sVCAM-1 promotes tumor growth and resistance to gemcitabine treatment in vivo but not in vitro." (PMID 33273652, 2020). "Overexpression of VCAM-1 in a murine pancreatic cancer cell line did not change the proliferation of cells compared to the control vector." (PMID 33273652, 2020). "VCAM-1 on pancreatic cancer cells might tethers THP-1 monocytes to cancer cells via counter–receptor interaction, providing a survival advantage to pancreatic cancer cells that infiltrate leukocyte-rich microenvironments." (PMID 29670110, 2018). "In pancreatic tumour tissues, PAK4KO did not change the ICAM-1 or VCAM-1 expression in the absence of gemcitabine, nor did it affect vascular normalisation, as shown by the unchanged NG2/CD31 and α-SMA/CD31 ratios." (PMID 41294859, 2025). "Although tumour cells are also capable of expressing ICAM-1 and VCAM-1, PAK1KD did not change the ICAM-1 or VCAM-1 expressions in pancreatic cancer cells." (PMID 41294859, 2025).
viral infection (23 papers, 2007 to 2025). "In this regard, the expression levels of VCAM1, vWF (von Willebrand factor), P‐selectin (a type‐1 trans‐membrane protein), and E‐selectin (an adhesion receptor) increased significantly upon viral infection in the mid‐aged mice ECs." (PMID 38098255, 2024). "Morphometric analysis then served to determine quantitative differences in the overall expression of VCAM-1 after virus infection." (PMID 37631979, 2023). "VCAM1 has been shown to regulate leukocyte trafficking and immune response against viral infections." (PMID 34422854, 2021). "VCAM-1 is a regulator of T-cell mediated inflammatory response and has been shown to contribute adversely towards immunopathology during viral infections." (PMID 28446152, 2017). "Vascular cell adhesion molecule-1 (VCAM-1) is strongly upregulated in hearts of mice with coxsackie virus-induced as well as in patients with viral infection-triggered dilated cardiomyopathy." (PMID 27501319, 2016). "The data is limited in virus infections, although it has been shown that Anandamide inhibits Theiler's virus induced VCAM-1 in brain endothelial cells resulting in reduced leukocyte transmigration across the BBB model." (PMID 25036379, 2014). "VCAM1 is another cell-adhesion molecule, known to play a role in regulating T cell-mediated inflammation and pathology, found to be up in the acute phase of viral infection." (PMID 37831367, 2024). "Thus, our findings underscore the potential role of VCAM-1 in regulating the immune response and inflammatory reactions against viral infections." (PMID 37831367, 2024). "Interestingly, 24 h after virus infection, vascular cell adhesion molecule 1 (Vcam-1) mRNA expression was downregulated." (PMID 36082118, 2022). "In addition, genes related to cell adhesion and migration, such as the β1 integrin vascular cell adhesion molecule 1 (VCAM-1), were also up-regulated by virus infection." (PMID 24708855, 2014). "Von Willebrand factor (vWf) has been shown to be released during CMV infection, and, among 39 patients with recent kidney transplantation and acute CMV infection, increased vWf and soluble vascular cell adhesion molecule 1 (sVCAM-1) in the peripheral blood were correlated with viral infection." (PMID 24678987, 2014). "Therefore, increasing Rta expression in the context of virus infection upregulates VCAM-1 expression at the cell surface." (PMID 17485528, 2007). "A number of higher expressed proteins are known to be induced by viral infection or interferon signaling (FRIL1 FRIH, VCAM1 and PSME1)." (PMID 31440143, 2019). "We found that mRNAs of ICAM-1, VCAM-1, E-selectin, fractalkine (CX3CL1), IL-8, TLR3, and Bcl2-A1 were activated by H1N1 viral infection and suppressed by TSL-1 treatment." (PMID 24073006, 2013). "These staining results suggest that the entry of virus specific effector T cell egressing the MedLNs on their way to the bronchial mucosa during viral infection, likely involves VCAM-1 rather than ICAM-1 and ICAM-2 mediated adhesions." (PMID 36895258, 2022). "The activation of this factor during early stages of viral infection leads to the expression of several immune response genes; such as pro-inflammatory cytokines (IFN-β, TNF-α, IL-6, IL-8), chemokines (RANTES) and adhesion molecules (ICAM-1, VCAM-1)." (PMID 17971236, 2007). "Thus, innate leukocyte trafficking through peribronchial blood vessels triggered by viral infection may involve alternative integrin-ligand pairs rather than ICAMs or VCAM-1." (PMID 36895258, 2022).
Cognitive impairment (22 papers, 2013 to 2026). Abnormal cognition is characterized by deficits in thinking, reasoning, or remembering. "In Alzheimer's disease (AD) and mild cognitive impairment, elevated VCAM‐1 levels have been associated with cognitive decline and hippocampal atrophy, and have even been incorporated into early blood biomarker panels." (PMID 41574640, 2026). "Among patients with PD, decreased PRR14 and increased VCAM-1 were associated with severer cognitive impairments and severer PD (H&Y), respectively." (PMID 36247752, 2022). "Of note, higher VCAM-1 levels were positively linked with cognitive impairment in a large cohort of elderly participants." (PMID 36247752, 2022). "Furthermore, decreased PRR14 was associated with severer cognitive impairments, and increased VCAM-1 was linked with severer PD and later AAO." (PMID 36247752, 2022). "Furthermore, we found that decreased PRR14 and increased VCAM-1 were linked with severer cognitive impairments and severer PD (H&Y), respectively." (PMID 36247752, 2022). "Taken together, our results suggest that oleracones ameliorated cognitive impairment by blocking TNF-α-induced increases in VCAM-1, thereby reducing leukocyte infiltration to the brain and modulating brain inflammation." (PMID 36768379, 2023). "Interestingly, plasma levels of soluble VCAM1 increase with aging in both humans and mice and positively correlate with cognitive impairment, while ICAM1 shows only a mild effect." (PMID 41272813, 2025). "In addition, systemic administration of anti-VCAM1 immunoglobulins and deletion of the Vcam1 gene in brain endothelial cells (BECs) was shown to reverse microglial reactivity and cognitive defects in mice." (PMID 34603320, 2021). "Due to the significant differences in the levels of VCAM‐1 and TNF‐α among groups, the effect of VCAM‐1 and TNF‐α on cognitive impairment was examined through mediation analysis." (PMID 39829127, 2025). "Animal experiments confirmed that the adhesion molecules VCAM-1 and LFA-1 played an important role in cognitive impairment." (PMID 36186141, 2022). "Our results showing an increase in markers of inflammation, VCAM1 and CD45, follows a similar paradigm to that documented in other progressive neurological diseases that correlate BBB leak with cognitive impairment." (PMID 23696861, 2013). "ICAM-1 and VCAM-1 were up-regulated in cerebral endothelial cells of CCH models, and the inhibition of ICAM-1 and VCAM-1 may protect cognitive impairment induced by chronic hypoperfusion." (PMID 35682903, 2022).